TDRD9 (tudor domain containing 9)
Diseases named in the same sentence as TDRD9 in open-access papers:
TDRD9 is named in the same sentence as 26 diseases in open-access papers, as found by Europe PMC text mining. Sharing a sentence is not in itself a finding about the gene and the disease. The quoted sentences say what the papers report.
Azoospermia (6 papers, 2018 to 2024). Absence of any measurable level of sperm,whereby spermatozoa cannot be observed even after centrifugation of the semen pellet. "TDRD9 silences Line-1 (L1) retrotransposons in the male germ line, and loss of TDRD9 leads to cryptozoospermia or azoospermia." (PMID 38764035, 2024). "TDRD9 is a member of the Tudor domain-containing protein family, primarily expressed in germ cells and closely related to azoospermia." (PMID 39670237, 2023). "The first study to identify a homozygous deletion mutation in the human TDRD9 gene suggested that the mutation is associated with nonobstructive azoospermia." (PMID 39174853, 2024). "In male infertility cases, TDRD9 has been reported to be involved in the silencing of long intersperm-1 retrotransposons, suggesting an association between TDRD9 mutations and nonobstructive azoospermia." (PMID 39174853, 2024).
Sepsis (6 papers, 2020 to 2025). Sepsis is defined as life-threatening organ dysfunction caused by a dysregulated host response to infection. "Circ-TDRD9 enhances the expression of Rab10 through the miR-223-3p/Rab10 axis, promoting acute lung injury induced by sepsis." (PMID 39996735, 2025). "Gene entities exhibiting stronger expression in the SIRS-ranked dataset included CFC1, CT62, lnc-DAAM2-1 and lnc-LTBP3-2 and in the sepsis-ranked dataset included TDRD9, DAAM2, OLFM4 and OLAH." (PMID 38332914, 2023). "It associates directly with TDRD9 and indirectly with SLC16A3 in pediatric sepsis, through MTF1, CD82, and G6PD." (PMID 32318053, 2020). "CD177 also exhibited strong direct connections to other hub entities GPR84 and TDRD9 in adult and pediatric sepsis and to GPR84 alone in pediatric septic shock and resolved SIRS." (PMID 32318053, 2020). "Gene entities shared between sepsis and severe sepsis response hubs are; TDRD9 – LIN7A, GPR84 – ENTPD7, PYCT1A and ZDHHC19, CD177 – DDAH2 and RGL4, SLC16A3 – DENND3 and MBD6, MYL9 – CMTM5, ITGB3, ITGA2B, NRGN, SELP and TREML1." (PMID 32318053, 2020). "Furthermore, we adopted DExH-box helicase/ATPase TDRD9 in the present study as potential candidate that others had identified in a study pertaining to sepsis." (PMID 38585145, 2024). "There was association of TDRD9 with CD177 and GPR84 in adult and pediatric sepsis." (PMID 32318053, 2020). "FGF13 is also associated with TDRD9 in pediatric sepsis and no other hub entities in adult sepsis." (PMID 32318053, 2020). "TDRD9 and ADGRE3 were chosen since they have been previously demonstrated to be part of the SRS1 signature in sepsis." (PMID 36389738, 2022). "In adult sepsis there is indirect interaction between GPR84, CD177, and TDRD9 through EXOSC4 and with CD177 through NECAB1." (PMID 32318053, 2020). "In adult sepsis, genes TDRD9, GPR84, and CD177 interacted via overlapped genes EXOSC4 (TDRD9 ↔ GPR84 ↔ CD177), ZDHHC19 (TDRD9 ↔ CD177) and NECAB1 (GPR84 ↔ CD177)." (PMID 32318053, 2020). "The profile is somewhat similar in pediatric sepsis with connections between GPR84 and TDRD9 directly and indirectly through instead DDAH2 and with CD177 through C19orf59 and RGL4." (PMID 32318053, 2020). "The majority of these clusters were not connected in most disease and control states, except for adult sepsis and adult SIRS with the gene clusters for TDRD9, CD177, GPR84, PCOLCE2, FGF13 and SLC16A3 interconnected at various points, either directly or through overlapped gene connections." (PMID 32318053, 2020).
Infertility (4 papers, 2020 to 2024). "Our clinical and genetic findings expand the understanding of the causative role of TDRD9 mutations in male-factor infertility." (PMID 39174853, 2024). "For TDRD9, we identified four infertile men with homozygous nucleotide substitutions predicted to affect the protein sequence: two homozygous LoF variants, c.3148dup p.(Val1050Glyfs*49) in M800 and c.3716+3A>G p.?" (PMID 39122675, 2024). "Of interest, some candidates related to sperm and infertility were identified, containing MORC1, TDRD9, ZFYVE21, ADGRB3, SPAG17, CKB, and WDR3, which may have effects on sperm motility and fertilization." (PMID 33477586, 2021).
lung carcinoma (4 papers, 2018 to 2023). "Having observed the CpG island hypomethylation-associated TDRD9 expression in a number of lung cancer cell lines (TDRD9-positive), we decided to investigate the role of TDRD9 in proliferation of these cells." (PMID 29515758, 2018). "Silencing of TDRD9 in lung cancer cell lines that express the gene causes a S-phase cell cycle arrest and increased DNA damage." (PMID 29515758, 2018). "This is consistent with a study where TDRD9 knockdown impaired proliferation of two lung cancer cell lines." (PMID 33374923, 2020). "New roles for TDRD9 have also been identified in lung cancer and was suggested as a potential therapeutic target." (PMID 33344664, 2020). "Taken together, our data suggest that TDRD9 plays a role in protecting a subset of lung cancer cells from replicative stress." (PMID 29515758, 2018). "We propose that TDRD9 plays a role in protecting a subset of lung carcinoma tumor cells from replicative stress." (PMID 29515758, 2018). "Then, we investigated the DNA methylation status of a region of the CpG island around the TSS (–234 to +109), in lung cancer cell lines with different levels of expression of TDRD9 using bisulphite genomic sequencing analyses of multiple clones." (PMID 29515758, 2018). "Thus, our results place TDRD9 as a marker for prognosis and as a potential therapeutic target in a subset of lung carcinomas." (PMID 29515758, 2018). "Therefore, we hypothesized that TDRD9 protects cells from DNA damage in TDRD9-positive lung carcinoma cells." (PMID 29515758, 2018). "In conclusion, these data suggest that TDRD9 does not control LINE-1 transcript expression in lung cancer cells." (PMID 29515758, 2018). "Interestingly, the gene was among the most differentially expressed genes in alveolar macrophages in smokers relative to non-smokers, and its knockdown in TDRD9-expressing lung carcinomas resulted in increased apoptosis." (PMID 36638096, 2023). "Interestingly, forced hypomethylation and de-repression of TDRD9 by 5-aza-2 ́-deoxycytidine treatment of TDRD9-negative cells, does not promote a stable de-repression of the gene, suggesting that TDRD9 expression does not confer a general selective advantage for all lung carcinoma tumor cells." (PMID 29515758, 2018). "However, expression of TDRD9 is not correlated with that of MAGEA1, MAGEA2, MAGEA3, or MAGEA4, which are CTA genes often expressed in lung cancer and melanomas." (PMID 29515758, 2018).
male infertility (3 papers, 2020 to 2024). The inability of the male to effect fertilization of an ovum after a specified period of unprotected intercourse. "As well as being situated within RD3L, rs35337422 also lies within an intron of the overlapping TDRD9 gene (encoding ‘tudor domain containing 9’), which is implicated in male infertility." (PMID 32227305, 2020). "Therefore, we conclude that the c.958delC and c.1115 + 3A > G mutations in TDRD9 may contribute to male infertility." (PMID 39174853, 2024).
lung adenocarcinoma (2 papers, 2018 to 2024). A carcinoma that arises from the lung and is characterized by the presence of malignant glandular epithelial cells. "TDRD9 (Tudor domain containing protein 9) is a RNA helicase that is typically germ-line associated, but has been shown to be a unfavorable prognostic marker in lung adenocarcinoma." (PMID 38585145, 2024). "Furthermore, TDRD9 expression is associated with poor prognosis in lung adenocarcinoma." (PMID 29515758, 2018). "Next we analyzed TDRD9 expression by conventional (RT-PCR) and quantitative reverse transcription-PCR (RT-qPCR) in lung adenocarcinoma (LA) cell lines and other non-small-cell lung carcinoma (NSCLC) cell lines." (PMID 29515758, 2018). "In fact, TDRD9 expression was significantly increased (more than 2-fold the median) in 13% (8 out of 59 samples) to 15% (34 out of 225) of the analyzed lung adenocarcinoma samples (P < 0.0001 with respect to the level in normal lung tissue)." (PMID 29515758, 2018). "Therefore, our analysis indicates that TDRD9 is highly expressed in a subset of lung adenocarcinoma and skin melanoma tumors." (PMID 29515758, 2018). "Analysis of TDRD9 expression in two sets of lung adenocarcinomas and skin melanomas showed that, in the cancer samples, values did not follow a normal (Gaussian) distribution (Shapiro-Wilk test P < 0.00001), suggesting that the positive outlier values did not result from random variance." (PMID 29515758, 2018). "Here we show that the TDRD9 gene is expressed in about 15% of lung adenocarcinomas and 30% of skin melanoma tumors, but not in the normal tissues." (PMID 29515758, 2018).
non-small cell lung carcinoma (2 papers, 2018 to 2020). A group of at least three distinct histological types of lung cancer, including non-small cell squamous cell carcinoma, adenocarcinoma, and large cell carcinoma. "TDRD9 is highly expressed in a subset of non-small cell lung carcinomas and derived cell lines through hypomethylation of its CpG island." (PMID 32828126, 2020). "Here, we show that TDRD9 is highly expressed in a subset of non-small cell lung carcinomas and derived cell lines by hypomethylation of its CpG island." (PMID 29515758, 2018).
brain tumors (1 paper, 2018). "Interestingly, SPN-E (the Drosophila homologue of TDRD9) and some other factors involved in piRNA metabolism, such as PIWI and AUB, are ectopically expressed in malignant brain tumors in Drosophila." (PMID 29515758, 2018).
cervix carcinoma (1 paper, 2018). "Previous data from our lab indicated that TDRD9 is also expressed in the cervix carcinoma cell line HeLa, therefore we also include this cell line in our assessment, as a positive control." (PMID 29515758, 2018).
colon cancer (1 paper, 2018). "Similar analysis of other types of tumors from TCGA showed that TDRD9 is expressed at high levels in a variable proportion of tumors, ranging from 1% in the case of colon cancer to 50% in acute myeloid tumors (AML)." (PMID 29515758, 2018).
colorectal tumors (1 paper, 2018). "TDRD9 has been previously identified as a putative Cancer/Testis antigen (CTA), in a microarray-based transcriptomic analysis of colorectal tumors." (PMID 29515758, 2018).
depression (1 paper, 2024). "qPCR results demonstrated that, compared to the normal control group, the expression of GRB10 and TDRD9 was significantly elevated in the blood of depression patients, while the expression of BCL7A, GPR18, KLRG1, and THEM4 was significantly reduced." (PMID 39867577, 2024). "For example, GRB10 and TDRD9, which are upregulated in depression, display variable expression patterns in different cancer types, reflecting their context-dependent roles." (PMID 39867577, 2024). "The results indicated that BCL7A (AUC: 0.656), GPR18 (AUC: 0.9677), GRB10 (AUC: 0.678), KLRG1 (AUC: 0.661), TDRD9 (AUC: 0.698), and THEM4 (AUC: 0.678) exhibit high diagnostic value for depression." (PMID 39867577, 2024). "This study conducted a comprehensive bioinformatics analysis, identifying six core genes (BCL7A, GPR18, GRB10, KLRG1, TDRD9, and THEM4) associated with depression and validating their diagnostic value in the context of the disorder." (PMID 39867577, 2024). "We identified six core genes (GRB10, TDRD9, BCL7A, GPR18, KLRG1, and THEM4) significantly associated with depression and cancer." (PMID 39867577, 2024). "The results showed that the expression levels of GRB10 and TDRD9 were significantly increased in depression patients compared to the control group, while the expression levels of BCL7A, GPR18, KLRG1, and THEM4 were significantly decreased, all with statistical significance." (PMID 39867577, 2024). "These pathways indicate that GRB10 and TDRD9 are involved in critical cellular processes such as survival signaling, stress adaptation, and metabolic regulation, which may play central roles in the development and progression of depression." (PMID 39867577, 2024). "To investigate the correlation between cancer and depression, we examined the expression of BCL7A, GPR18, GRB10, KLRG1, TDRD9, and THEM4 across various cancer types using the TCGA database." (PMID 39867577, 2024). "Among them, GRB10 and TDRD9 were significantly upregulated, while BCL7A, GPR18, KLRG1, and THEM4 were significantly downregulated in patients with depression." (PMID 39867577, 2024). "To more accurately predict and assess the progression of depression, we constructed a nomogram model for depression diagnosis based on the core genes (GRB10, TDRD9, BCL7A, GPR18, KLRG1, and THEM4) using the rms package." (PMID 39867577, 2024). "We identified six core genes (BCL7A, GPR18, GRB10, KLRG1, TDRD9, and THEM4), confirming their critical value in diagnosing depression." (PMID 39867577, 2024). "In depression, GRB10 and TDRD9, involved in cell growth and stress responses, exhibited elevated expression, while BCL7A, GPR18, KLRG1, and THEM4, linked to immune regulation and apoptosis, showed reduced expression, suggesting dysregulated cellular signaling and impaired immune function." (PMID 39867577, 2024).
gram-negative bacterial infections (1 paper, 2020). Infections caused by bacteria that show up as pink (negative) when treated by the gram-staining method. "As markers GPR84, KLRK1, and TDRD9 were not represented in dataset E-GEOD-6269 (Affymetrix chip HG-U133A), interaction profiling of these genes was omitted from the gram-positive and gram-negative bacterial infection group dataset." (PMID 32318053, 2020).
influenza (1 paper, 2024). An acute viral infection of the respiratory tract, occurring in isolated cases, in epidemics, or in pandemics; it is caused by serologically different strains of viruses (influenzaviruses) designated A, B, and C, has a 3-day incubation period, and usually lasts for 3 to 10 days. "The ten common DEGs (PCOLCE2, HLA_DPA1, LOC653061, TDRD9, MPO, HLA_DQA1, MAOA, S100P, RAP1GAP, and CA1) that were obtained by overlapping genes from computing the three algorithms [LASSO regression, SVM-RFE algorithms, and RF are candidate key genes for severe influenza." (PMID 38454348, 2024). "In contrast, PCOLCE2, TDRD9, MPO, MAOA, RAP1GAP, and S100P expression was higher in the severe influenza group compared to the non-severe influenza group in the training cohort, similar to the findings in the validation cohort." (PMID 38454348, 2024).
melanoma (1 paper, 2018). A malignant, usually aggressive tumor composed of atypical, neoplastic melanocytes. "Similarly, TDRD9 expression is increased in 25% (6 out of 24) to 32% (13 out of 40) of the melanoma samples (P < 0.0001 with respect to the level in normal skin)." (PMID 29515758, 2018).
type II diabetes (1 paper, 2024). "The high TDRD9 subgroup was significantly enriched in DNA replication, ribosome, and RNA polymerase, whereas the low TDRD9 subgroup was enriched in type II diabetes, folate biosynthesis, and sulfur metabolism." (PMID 39867577, 2024).
cancer (5 papers, 2018 to 2024). A tumor composed of atypical neoplastic, often pleomorphic cells that invade other tissues. "Many RNA metabolism factors affect genome stability, making it therefore possible that interactions created by the ectopic expression of TDRD9 in cancer cells contribute to alleviate replication stress." (PMID 29515758, 2018). "As nothing was known about the role of TDRD9 in cancer, therefore we decided to search for abnormal TDRD9 expression levels in different cancer databases and cell lines." (PMID 29515758, 2018). "As a first step to investigate a possible role of TDRD9 in cancer we explored publicly available cancer gene expression sets using the ONCOMINE database." (PMID 29515758, 2018). "Conversely, THEM4, TDRD9, and KLRG1, which act as risk factors in some cancers, might contribute to tumor progression through immune evasion mechanisms or by impairing apoptosis pathways." (PMID 39867577, 2024). "For example, overexpression of GRB10 and TDRD9 may enhance cancer cell proliferation, while downregulation of BCL7A, GPR18, KLRG1, and THEM4 could contribute to reduced immune surveillance and tumor evasion." (PMID 39867577, 2024). "For instance, BCL7A and GRB10 showed protective roles in some cancers, possibly through mechanisms such as enhancing immune infiltration or suppressing oncogenic pathways, while THEM4, TDRD9, and KLRG1 acted as risk factors in others, potentially by inhibiting tumor suppressor functions." (PMID 39867577, 2024). "Therefore, how does TDRD9 expression favor cancer cell proliferation?" (PMID 29515758, 2018). "Although DTA picked genes TDRD9 and TDRD12, which belong to the same family, we found their expression pattern to be quite different for cancer samples." (PMID 34503106, 2021). "Genes such as BCL7A and GRB10 may exert anti-cancer effects by promoting immune cell infiltration, whereas KLRG1, THEM4, and TDRD9 might suppress immune cell infiltration, facilitating tumor progression." (PMID 39867577, 2024).
tumor (2 papers, 2018 to 2024). "We show that TDRD9-expressing cell lines and tumor samples display a strong hypomethylation of the TDRD9 CpG island." (PMID 29515758, 2018). "Finally, TDRD9 silencing caused hypersensitivity to the replication stress inducer aphidicolin, while overexpression of the protein increased resistance to the drug, suggesting that TDRD9 protects from replicative stress to TDRD9-positive tumor cells." (PMID 29515758, 2018). "Therefore, we speculate that hypomethylation of the TDRD9 CpG island is a specific tumor type-dependent event that is favored by the selective advantage conferred by the expression of TDRD9." (PMID 29515758, 2018). "Taken together, these data suggest that the TDRD9 function in tumor cells is not related to control of LINE-1 expression." (PMID 29515758, 2018). "In fact, most (98%) of the tumor samples that did not express TDRD9 showed a high level of TDRD9 methylation (fraction of methylated cytosines > 0.5)." (PMID 29515758, 2018).
benign tumors (1 paper, 2020). "Methylarginine binding genes TDRD1 and TDRD9, had overall low expression in HGSOC and benign tumors." (PMID 33374923, 2020).
TDRD9 also shares sentences with these, for which no sentence is quoted: cryptorchidism (1 paper); Cryptozoospermia (1); liver cancer (1); Sertoli Cell-Only Syndrome (1); skin melanomas (1); thyroid cancer (1); virus infection (1).